TMEM234 (transmembrane protein 234)
Synonyms: C1orf91; RP4-622L5; dJ622L5.7; FLJ90779; AASL548; PRO1105
Tractability: Antibody: UniProt predicts a signal peptide or a membrane-spanning region.
Gene: Protein-coding gene on chromosome 1 (32,214,472 to 32,222,359, reverse strand). Ensembl gene ENSG00000160055.
Subcellular location: Membrane
Subcellular location (Human Protein Atlas): Vesicles
Gene Ontology:
Molecular function: protein binding
Cellular component: membrane
Genetic constraint (gnomAD): Loss-of-function variants: 24 observed, 20.62 expected, observed/expected ratio (o/e) 1.16, 90% interval 0.84 to 1.63. The upper end of that interval is the gene's LOEUF score, 1.63, which puts it in group 6 of 6, group 1 being the genes least tolerant of losing a copy. Missense variants: 137 observed, 173.86 expected, observed/expected ratio (o/e) 0.79, 90% interval 0.69 to 0.91. Synonymous variants: 83 observed, 78.25 expected, observed/expected ratio (o/e) 1.06, 90% interval 0.89 to 1.27.
Homologues: Orthologues: guinea pig TMEM234 (89% identical), pig TMEM234 (88% identical), dog TMEM234 (87% identical), mouse Tmem234 (85% identical), rabbit TMEM234 (85% identical), rat Tmem234 (81% identical), macaque TMEM234 (61% identical).
Diseases named in the same sentence as TMEM234 in open-access papers:
TMEM234 is named in the same sentence as 2 diseases in open-access papers, as found by Europe PMC text mining. Sharing a sentence is not in itself a finding about the gene and the disease.
TMEM234 shares sentences with these, for which no sentence is quoted: hepatocellular carcinoma (1 paper); tumor (1).